TWIST1 (twist family bHLH transcription factor 1)
Diseases named in the same sentence as TWIST1 in open-access papers (continued):
Sharing a sentence is not in itself a finding about the gene and the disease.
hepatocellular carcinoma (continued). "TWIST1 potently induces the EMT and also has a critical role in the occurrence of VM in hepatocellular carcinoma." (PMID 25895023, 2015). "In addition, Trabid cooperates with Twist1 to specifically removes RNF8-mediated K63 ubiquitin chains from Twist1, thus suppressing hepatocellular carcinoma metastasis." (PMID 36202787, 2022). "Previous studies on hepatocellular carcinoma, breast and colorectal cancers showed that sOPN could contribute to the metastasis through enhancing EMT-related transcription factors such as TWIST1, SNAI1 and SNAI2 and then decreasing the adhesion of tumor cells." (PMID 34070192, 2021). "Twist1 has also been shown to be expressed in cytoplasm but not nucleus of human hepatocellular carcinoma (HCC), whereas E-cadherin was localized on membranes." (PMID 23133563, 2012). "Further, hepatocellular carcinoma-related protein 1 (HCRP1), a protein responsible for degradation of ubiquitinated membrane receptors, is downregulated in HCC and correlated with increased EGFR activation, EMT, Snail and Twist1 expression." (PMID 34067095, 2021). "The interaction between SPZ1 and TWIST1 was further evaluated in tumors and adjacent healthy liver tissues from SPZ1 transgenic mice and patients with hepatocellular carcinoma (HCC)." (PMID 30154425, 2019). "In agreement, Twist1 expression is positively correlated with up-regulation of VEGF in hepatocellular carcinoma cells and HCC specimens with positive Twist1 expression have a higher micro-vessel density than those without Twist1 expression." (PMID 28099910, 2017).
melanoma (83 papers, 2012 to 2025). A malignant, usually aggressive tumor composed of atypical, neoplastic melanocytes. "A progressive loss of ZEB2/SNAIL2 and a gain in TWIST1/ZEB1 expression were observed along the transition from melanocytes to malignant melanoma." (PMID 32759677, 2020). "In particular, a reduced expression of ZEB2 and SNAIL2 in favour of an increased expression in ZEB1 and TWIST1 was linked to E-cadherin loss, increased invasion properties and poor clinical outcomes in human melanoma." (PMID 32858889, 2020). "Downregulation of AC in melanoma cells was also reported to induce E-cadherin loss and, inversely, to increase expression of TWIST1, which is in accordance with a more aggressive phenotype." (PMID 33121001, 2020). "CADM1 was inversely associated with TWIST1 across melanoma genotypes and TWIST1 occupied the proximal CADM1 promoter." (PMID 30911007, 2019). "If melanoma acts as an open-wound in the skin, then Twist1 might be upregulated in tumor-associated keratinocytes as an adaptive response to close this wound." (PMID 39229155, 2024). "TWIST1 has also been associated with both melanoma stemness- and tumor-initiating properties." (PMID 37511550, 2023). "We herein wondered whether high ZEB1/TWIST1 expression may be associated with the resistance to MAPKi in melanoma, with the final aim of testing whether targeting these factors in combination with MAPKi could prevent the emergence of resistance." (PMID 27596438, 2016). "In the present investigation, when sorafenib was combined with fisetin, fisetin potentiated the EMT inhibitory effect of sorafenib and effectively down regulated the expression of Twist1 transcription factor in BRAF-mutated melanoma cells in vitro as well as in xenograft tumors." (PMID 26517521, 2016). "Indeed, ZEB2 and SNAIL2 are expressed in normal adult melanocytes, and a switch in EMT‐TFs expression, characterized by a loss of ZEB2 and SNAIL2 and an upregulation of ZEB1 and TWIST1, occurs during melanoma progression." (PMID 27596438, 2016). "The results revealed that melanoma cells exhibited substantial expression of critical stemness-associated genes, namely HIF1A, EPAS1, TWIST1 and EZH2." (PMID 41383633, 2025). "The downregulation of Slug and Zeb2, and upregulation of Zeb1, Snail and Twist1 promote differentiation and metastasis in melanoma cells." (PMID 37181747, 2023). "Previous studies revealed that during melanoma progression, melanoma cells develop stem-cell like properties associated with the expression of SOX10, EZH2 transcription factors, EMT phenotypic switch regulators TWIST1/ZEB1, and the surface receptor CD172." (PMID 35269844, 2022). "In various malignancies, such as sarcoma, melanoma, and glioblastoma, Twist1 is found that regulates tumor cell invasion and metastasis." (PMID 36254231, 2022). "For example, ZEB1 promotes the initiation and metastatic progression of melanoma which is supported by TWIST1, whilst ZEB2, supported by SNAI2, acts as a melanoma tumour suppressor." (PMID 35278142, 2022). "The expression of miR-10b is transcriptionally activated by BRAFV600E-mediated upregulation of Twist family BHLH transcription factor 1 (TWIST1) in melanoma cells." (PMID 33435156, 2021). "In melanoma, TWIST1 can directly act on the CADM1 promoter region to inhibit the expression of CADM1 and promote tumor metastasis." (PMID 34395444, 2021). "In particular, a reduced expression of ZEB2 and SNAIL2, in favor of an increased expression in ZEB1 and TWIST1, has been linked to MITF downregulation, E-cadherin loss and increased invasive properties of human melanoma cells." (PMID 33121001, 2020). "High levels of ZEB1/TWIST1 expression undoubtedly promote an invasive phenotype in melanoma, including decreased E-Cadherin, MITF, and increased expression of Vimentin, SPARC, and MMPs." (PMID 32759677, 2020). "TWIST1 contributes to an EMT-like phenotype switch in melanoma that enhances migratory and invasive function." (PMID 30911007, 2019).
melanoma (continued). "Although TWIST1 mRNA and protein expression are positively regulated by ERK1/2 in melanoma, there was little change in TWIST1 mRNA or protein expression upon ERK1/2 hyperactivation in H6244-R or L6244-R cells." (PMID 35582726, 2019). "In this study, we performed expression profiling to identify the TWIST1-regulated transcriptome of melanoma cells." (PMID 30911007, 2019). "We explored the TWIST1-regulated transcriptome through expression array analysis using invasive mutant BRAF melanoma cells as a model." (PMID 30911007, 2019). "Our group has previously demonstrated that TWIST1 plays a role in the ability of melanoma cells to invade through the dermal layer in part by up-regulating the matrix metalloprotease, MMP-17." (PMID 30911007, 2019). "Previous findings indicate that TWIST1 promotes invasion via the upregulation of MMP1 in human melanoma cells." (PMID 30975980, 2019). "Knockdown of Gli2 restored sensitivity to vemurafenib-resistant melanoma cells while TWIST1, which is overexpressed in colon cancer, plays a crucial role in the resistance of these tumors to irinotecan." (PMID 30167084, 2018). "High FOSL1 and altered TWIST1 expression were found to be correlated with shortened survival in the cohort of melanoma patients." (PMID 30089785, 2018). "In melanocytes, the expressions of Snail2 and Zeb2 were found to be higher and act as oncosuppressor whereas Twist1 and Zeb1 promote neoplastic transformation of melanocytes and aberrantly reactivate in melanoma." (PMID 28137308, 2017). "Since apigenin inhibited the expression level and promoter activity of Twist1 in melanoma A375 cells, we wondered if apigenin reversed the EMT in A375 cells." (PMID 26911838, 2016). "All these data suggest that the inhibitory effects of apigenin on melanoma migration and invasion are due to, at least in part, the reduction of Twist1 expression." (PMID 26911838, 2016). "We will further investigate if the changed expressions of EMT markers, due to apigenin treatment or knockdown of Twist1 by siRNA, contribute to the inhibition of invasion in the melanoma cell model." (PMID 26911838, 2016). "Our group has also demonstrated the efficacy of TWIST1 siRNA in reducing melanoma growth in vivo via inhibition of apoptosis." (PMID 27876874, 2016). "Twist1 is a transcription factor that frequently expressed in a wide array of human cancers including melanoma." (PMID 26911838, 2016). "Fisetin and sorafenib reduced the expression of Snail1, Twist1, Slug and ZEB1 in BRAF-mutated melanoma cells." (PMID 26517521, 2016). "To further investigate if Twist1 involved in apigenin-mediated migration and invasion inhibition in melanoma cells, we overexpressed Twist1 in A375 cells by transient transfection of a Twist1-expressing construct pcDNA3.1-Twist1." (PMID 26911838, 2016). "We showed for the first time that targeting miRNA by cordycepin indicates a new mechanism of cordycepin-induced suppression of tumor metastasis and miR-33b/HMGA2/Twist1/ZEB1 axis plays critical roles in regulating melanoma dissemination." (PMID 25868853, 2015). "By targeting HMGA2 and Twist1, miR-33b attenuated melanoma migration and invasiveness upon cordycepin exposure." (PMID 25868853, 2015). "Recent research showed that a reversible EMT-TF (transcription factor) reprogramming involving upregulation of ZEB1/TWIST1 paralleled by downregulation of SNAIL2/ZEB2 occurs in human melanoma." (PMID 25051363, 2014). "We therefore investigated the expression of PAR-1 and TWIST-1 in sections of non-melanoma skin dysplasia." (PMID 23675494, 2013). "Moreover, in line with a previous study identifying Twist Family BHLH Transcription Factor 1 (TWIST1) as an anti-apoptotic modulator in melanoma, we observed downregulation of TWIST1 upon combined treatment with TGFβ1 and MEKi." (PMID 39709491, 2024).
melanoma (continued). "In melanoma, we previously showed that, during melanoma progression, a switch in the EMT-TFs’ expression occurs, with a loss of ZEB2 and SNAI2 expression and the upregulation of ZEB1 and TWIST1 expression." (PMID 38398085, 2024). "Substantiated investigations have elucidated that the downregulation of DLL3 can attenuate lipopolysaccharide-induced inflammation, inhibit migration, and impede invasion of melanoma cells through the inhibition of Twist1-mediated epithelial-mesenchymal transition." (PMID 38036577, 2023). "Indeed, primary melanoma cells showed an upregulation of Mitf and Twist1 and a downregulation of Snai1 and Prrx1 levels upon Loxl3 silencing." (PMID 35267510, 2022). "Moreover, downregulation of AC in melanoma cells induced E-cadherin loss and, inversely, increased expression of the epithelial-mesenchymal transition (EMT)-associated protein TWIST1, which is in accordance with a more aggressive phenotype." (PMID 32858889, 2020). "We also investigated the correlation of the seven prognostic-associated TBCs between MMP-related genes (MMP2, MMP9, MMP7, MMP14, BSG, EGFR, MMP1, MMP3) and EMT-associated genes (TWIST1, VIM, CDH2, ACTA2, ZEB1), which also indicated a central role of TBCs in melanoma." (PMID 33194704, 2020). "Moreover, this switch from ZEB2/SNAIL2 to TWIST1/ZEB1 was a significant factor of poor prognosis for melanoma patients." (PMID 32759677, 2020). "Taken together, these results suggest that TWIST1 regulates EMT pathway-related genes in melanoma." (PMID 30911007, 2019). "The work presented here demonstrates a previously unknown function of TWIST1 in the metastatic progression of human melanoma." (PMID 30911007, 2019). "Interestingly, a significant proportion of ZEB1‐negative melanoma samples from patients with primary resistance displayed strong TWIST1 staining." (PMID 27596438, 2016). "Furthermore, an inhibitor of STAT3 reduced downstream activity of TWIST1, which led to impeded migration and invasion of melanoma cells." (PMID 27876874, 2016). "While our study was mainly focused on ZEB1, TWIST1 is also frequently activated in melanoma." (PMID 27596438, 2016). "The partial reversal of EMT in melanoma cells after apigenin treatment may due to a reduction in Twist1 expression." (PMID 26911838, 2016). "HMGA2 or Twist1 overexpression reverted cordycepin-mediated reduction of melanoma motility." (PMID 25868853, 2015). "To determine whether changes of these gene expressions were dependent on the activities of HMGA2 and Twist1, we transfected melanoma cells with mock, HMGA2 or Twist1 constructs." (PMID 25868853, 2015). "Overexpression of Twist1 in melanoma augmented melanoma migration and invasion via MMP-1." (PMID 25868853, 2015). "To assess whether there is an association between the levels of HMGA2, Twist1 or ZEB1 and miR-33b in melanoma, we analyzed their levels in 72 melanoma patient samples." (PMID 25868853, 2015). "To determine whether the levels of ZEB1 and MITF were predictive of the patients’ response to MAPKi, we performed immunohistochemical staining for ZEB1, MITF but also TWIST1 on a cohort of 70 human BRAFV600 melanoma samples from patients whose response to the treatment was known." (PMID 27596438, 2016). "In melanoma cells, PTX3 production was found to stimulate the expression of EMT-related factors, such as TWIST1, further supporting its role in promoting tumor metastasis." (PMID 39594709, 2024). "PTX3, a key factor in a subtype of invasive melanoma, can mediate the expression of the EMT transcription factor TWIST1 through a TLR4/MYD88/IKK/NF-κB signaling pathway and drive melanoma cell migration." (PMID 37277447, 2023). "In melanoma and head and neck squamous cell carcinoma, Notch4 signalling induces EMT by stimulating the expression of EMT markers such as Vimentin and Twist1 and downregulating the expression of E-cadherin." (PMID 37108670, 2023).
melanoma (continued). "It has been proven that following the activation of the NRAS / BRAF pathway in melanoma, genes promoting cell proliferation such as SNAIL2 and ZEB2 are replaced by those regulating the migration such as ZEB1 and TWIST1." (PMID 35820816, 2022). "In melanoma cases, it has been reported that apigenin activates the cleaved caspase-3 and PARP expression sites; downregulates Twist1, MMP-2/9, VEGF, p-mTOR, ERK1/2 proteins, and p-AKT; and deactivate FAK/ERK1/2 pathways." (PMID 35965686, 2022). "The assays confirmed that after the transfection of cells with TWIST1, EMT pathway proteins were activated, and the invasion and migration abilities of melanoma A375 cells were enhanced." (PMID 35894206, 2022). "For melanoma, knockdown of DLL3 inhibits inflammatory stimulation-induced melanoma cell migration and invasion by blocking Twist1-mediated epithelial-mesenchymal transition (EMT)." (PMID 36338696, 2022). "Evidence from in vivo models and human clinical samples has led to a proposed model of phenotype switching during melanoma progression, fine-tuned by ZEB1/2, TWIST1, and SNAIL2, as well as MITF expression." (PMID 35267510, 2022). "Interfering Twist1 inhibited epithelial-mesenchymal transition (EMT) and limited lipopolysaccharide-induced inflammation, migration, and invasion in A2058 melanoma cells with the decrease of MMP1/9, VEGF, TNF-α, and IL-6." (PMID 35321317, 2022). "The high ZEB1/TWIST1, low MITF, high AXL state promotes an invasive, dedifferentiated phenotype in melanoma while the high ZEB2/SLUG, high MITF, low AXL state promotes an anti-invasive, proliferative, differentiated phenotype." (PMID 35008286, 2021). "They found that EMT-inducing transcription factors undergo a profound reorganization in favor of TWIST1 and ZEB1 during melanoma metastatization." (PMID 33980826, 2021). "Therefore, while ZEB1 and TWIST1 harbor oncogenic activities in melanoma, ZEB2 and SNAIL2, which are expressed in normal melanocytes and are required for their proper differentiation, they may act as oncosuppressive proteins in this specific neural crest-derived lineage." (PMID 32759677, 2020). "We found that TWIST1 acts to repress CADM1 levels and suppression of CADM1 appears to enhance traits needed for metastatic dissemination of melanoma." (PMID 30911007, 2019). "For example TWIST1 and ZEB1 increase the metastatic potential of melanoma cells whereas SNAI2 (SLUG) and ZEB2 decrease it." (PMID 29432466, 2018). "Collectively, 50% of primary resistant melanomas exhibited a strong staining for ZEB1 and/or TWIST1." (PMID 27596438, 2016). "During melanoma progression, EMT-inducing transcription factors (Snail1, Twist1, ZEB1 and Slug) are regulated by BRAF/MEK/ERK (MAPK) and PI3K signaling." (PMID 26517521, 2016). "The cordycepin treatment downregulated the expression of ZEB1, HMGA2 and TWIST1 by more than 50% but had minimal effects on ADAM9, RAC1, SALL4, CTNNB1, ZEB2 and YES1 in these two melanoma cell lines." (PMID 25868853, 2015). "We also found that melanoma migration and invasiveness was mediated by miR-33b though directly targeting high mobility group AT-hook 2 (HMGA2), Twist1 and human zinc finger E-box binding homeobox 1 (ZEB1)." (PMID 25868853, 2015). "In melanoma, overexpression of ZEB1 and TWIST1 with low expression of ZEB2 significantly shortens metastasis-free survival." (PMID 26515895, 2015). "Moreover, MAPK pathway activation induces FRA1 in melanoma cells, which promotes transcription factor reprogramming, favoring ZEB1 and TWIST1 expression, transcription factors that induce EMT-like states." (PMID 41286309, 2025). "TWIST1 and MYC demonstrated substantial expression in C3 HHATL+ melanoma cells." (PMID 41383633, 2025). "Differential BMI1, TWIST1, and SNAI2 mRNA expression patterns correlate with malignancy type in a spectrum of common cutaneous malignancies, including basal cell carcinoma, squamous cell carcinoma, and melanoma." (PMID 40332096, 2025).